STAT3 (signal transducer and activator of transcription 3)
Diseases named in the same sentence as STAT3 in open-access papers (continued):
Sharing a sentence is not in itself a finding about the gene and the disease.
Parkinson disease (28 papers, 2010 to 2025). A progressive degenerative disorder of the central nervous system characterized by loss of dopamine producing neurons in the substantia nigra and the presence of Lewy bodies in the substantia nigra and locus coeruleus. "Among these factors, CTCF, MEF2A, and STAT3 have been associated with Alzheimer’s, Huntington’s, and Parkinson’s diseases." (PMID 34720873, 2021). "The FDA-approved Janus kinase inhibitors (JAKi) (i.e., jakinibs) are used to diminish the effects from STAT3 activation and to control progression of neurodegenerative diseases such as Alzheimer’s and Parkinson’s diseases." (PMID 39508990, 2025). "Conversely, numerous studies indicate that the activation of JAK2/STAT3 inhibits the onset of Alzheimer’s, Parkinson’s, and myocardial-cerebral vascular diseases." (PMID 38794201, 2024). "They found that miR-93 directly targets STAT3, and increasing miR-93 helps to protect cells that produce dopamine in Parkinson’s mice." (PMID 38463392, 2024). "The ability of BHB to suppress pyroptosis via inhibiting the STAT3/NLRP3/GSDMD axis was previously documented in Parkinson’s disease models." (PMID 37841914, 2023). "Interestingly, GSEA also indicated LCNM+-enriched expression of genes that are regulated by several TFs—ATF4, EBF3, STAT3, and MEF2D—all of which are protective against Parkinson’s disease, or associated with NM content in dopamine cells of the substantia nigra." (PMID 41278831, 2025). "For example, STAT3 phosphorylation and neuronal autophagy are promoted by brain-derived neurotrophic factor (BDNF), a promising agent for targeting Parkinson’s disease." (PMID 39508990, 2025). "For instance, in Parkinson’s disease (PD), diminished SOCS3 levels could contribute to STAT3 overactivation, potentially worsening microglial activation and neurodegeneration." (PMID 40755762, 2025). "For example, activation of the STAT3/HIF1α axis promoted α-synuclein-induced ferroptosis, with GPX4 suppression and iron dyshomeostasis in a Parkinson’s disease model, whereas pharmacological STAT3 inhibition reduced lipid ROS and iron accumulation in microglia." (PMID 41304754, 2025). "Stat3 was reported to be capable of binding to the NLRP3 promoter and enhanced NLRP3 transcription to participate in neuronal pyroptosis, mechanical allodynia, and Parkinson's disease." (PMID 39601144, 2024).
allergic disease (27 papers, 2011 to 2025). An immune response that occurs following re-exposure to an innocuous antigen, and that requires the presence of existing antibodies against that antigen. "The patients with ATM predominantly presented ataxia/telangiectasia (46.2%) and infections (32.1%), while allergy (52.6%) and infection (94.4%) were the dominant first manifestations in STAT3 (AD-LOF) and DNMT3B/ZBTB24 mutations, respectively." (PMID 36544766, 2022). "Additionally,the IL-6/JAK/STAT3 signalling pathway has been shown to be associated with mast cell degranulation and allergic reactions." (PMID 38045687, 2023). "Next, we established an allergy model by sensitizing STAT3-CKO and control mice with dust mites (HDM) and OVA." (PMID 41212476, 2025). "The C16 lipid ceramide also showed regulatory effects on DC by decreasing the expression of Stat3 and Rela, both being involved in cell signaling pathways that regulate allergic reactions." (PMID 36520269, 2023). "STAT1, STAT3, TLR8, IL13, RFX5 gene polymorphisms have been demonstrated as susceptibility loci for the immune dysregulation in various inflammatory and allergic diseases." (PMID 32886659, 2020). "This case underscores the inherent diagnostic difficulty of HIES in young children with confounding co-morbidities (food and inhalant allergies which are unusual features for STAT3-HIES, transiently low IgA, aspiration pneumonia, etc.)." (PMID 22126402, 2011). "The role of STAT3 in Treg/Th17 imbalance in widely reported for allergic diseases." (PMID 32448264, 2020). "PKC and ceramide can also activate the STAT3 pathway and then act on NF-κB and PTPRC, thus regulating allergic reaction." (PMID 35804699, 2022). "We also included two soluble cytokine receptors (sIL4RA and sIL13RA2) and an exploratory component consisting of three allergy-related transcription factors (FOXP3, STAT3 and STAT6)." (PMID 26352148, 2015). "The USP7-STAT3-Granzyme-PAR-1 axis significantly influenced Th2 cell differentiation by regulating the production and activity of GzmA and GzmB, as well as the phosphorylation of STAT3 by USP7, particularly in the production of IL-5 and IL-13, which played a key role in allergic diseases." (PMID 40893770, 2025). "This study provides a possibility that the improvement effect of SD treatment on allergies and inflammation in AR mice may be related to the TLR4/TRAF6/NF-κB and IL-6/ROR-γt/STAT3 pathways and intestinal microflora modulation." (PMID 36276863, 2022). "The fibroblast growth factor-inducible 14 (Fn14) receptor, the signal transducer and activator of transcription 3 (STAT3), the peroxisome proliferator-activated receptor (PPAR β/δ), and MALT1 protease activity have been proposed as therapeutic strategies in allergy and anaphylaxis." (PMID 35371072, 2022). "His clinical phenotype had some overlap with STAT3 deficiency, and did not present with hallmarks of DOCK8 deficiency including allergic diseases and cutaneous viral infections." (PMID 36703986, 2022). "In line with present observations, HDM/DNCB stimulation upregulated the T-bet, STAT3, and GATA3 and other allergy mediating cytokines (IL-4, IL-5, IL-10, IL-13, and IFN-γ) and chemokine (TARC) expression levels, while these were dose-dependently downregulated following SHE treatment." (PMID 32824648, 2020).
cardiomyopathy (27 papers, 2012 to 2026). A disease of the heart muscle or myocardium proper. "As a transcription factor, STAT3 has been implicated to protect hearts from acute ischemic injury under stressful conditions, and loss of STAT3 will result in cardiomyopathy." (PMID 27119006, 2016). "In conclusion, our study elucidates that PatA ameliorates HG + PA- or STZ-induced cardiomyopathy through the modulation of the JAK2/STAT3 signaling pathway." (PMID 38794201, 2024). "Our findings illustrate that PatA mitigates the effects of HG + PA- or STZ-induced cardiomyopathy by acting on the JAK2/STAT3 signaling pathway." (PMID 38794201, 2024). "STAT3 acts as a protective signal against DOX-induced cardiomyopathy by inhibiting reduction of cardiac contractile genes and inducing cardiac protective factors." (PMID 35293279, 2022). "Recently, impaired STAT3 signaling was reported to contribute to the etiology of DOX-induced cardiomyopathy." (PMID 35293279, 2022). "Recent studies have shown that STAT3 pathway activation participates in the pathophysiological development of DCM, and inhibition of STAT3 attenuates cardiomyopathy in STZ-induced T1DM." (PMID 34621323, 2021). "There are several studies that found myocardial protection by STAT3 against doxorubicin-induced cardiomyopathy." (PMID 32178385, 2020). "STAT3 has been shown to be involved in cardioprotection against Dox, whereby the overexpression of STAT3 in the heart was shown to be protective against Dox-induced cardiomyopathy." (PMID 31709266, 2019). "Our salient results revealed for the first time that SPRC mediates the protective function of gp130/STAT3 in response to Dox-induced cardiomyopathy in both cardiomyocytes and hearts." (PMID 27537522, 2016). "This ongoing fibrosis in infected STAT3 KO resulted in impaired cardiac function, since collagen is known to depress cardiac function in experimental models as well as in patients with cardiomyopathies." (PMID 22675647, 2012). "Moreover, one previous study shows that the protein expression of STAT3 is down-regulated in the patients with end-stage of DCM, while overexpression of STAT3 in the heart protects against doxorubicin-induced cardiomyopathy." (PMID 23818963, 2013). "Phosphorylation at site S727 drives STAT3 into the mitochondria (mtSTAT3) to participate in electron transport chain activity, while phosphorylation at site Y705 drives STAT3 into the nucleus, where it functions as a transcriptional activator and influences the pathophysiology of cardiomyopathy." (PMID 39200351, 2024). "In response to IL-27, gene expression of TBX21, EOMES, and CXCL9, which are activated downstream of STAT1, STAT3, and STAT5 phosphorylation, was lower in patients with cardiomyopathy (i.e., the G1 and G2 groups) than that in uninfected subjects." (PMID 34061845, 2021). "The signal transducer and activator of transcription 3 (STAT3), one downstream signaling molecule of CRT, plays an important role in the progress of cardiomyopathy." (PMID 23818963, 2013). "In summary, although more distinct gp130/STAT3-dependent mechanisms still remain elusive, based on our studies, the cardioprotective effects of SPRC are possibly accounted for gp130/STAT3-mediated protection against Dox-induced cardiomyopathy." (PMID 27537522, 2016). "However, if Prmt7 is depleted after menopause, STAT3 signaling is dysregulated due to decreased negative feedback by Socs3, eventually resulting in more severe cardiomyopathy." (PMID 38486105, 2024).
experimental autoimmune encephalomyelitis (27 papers, 2012 to 2026). An autoimmune demyelinating disease of the central nervous system that is produced experimentally in animals by the injection of homogenized brain or spinal cord in Freund's adjuvant. "ERS can activate the JAK1–STAT3 pathway in experimental autoimmune encephalomyelitis, and the activation of STAT3 depends on PERK, which is the core component of ERS." (PMID 40384344, 2025). "LIF inhibited Th17 cells differentiation by exerting an opposite effect on STAT3 phosphorylation, which is required for Th17 cell differentiation, in experimental autoimmune encephalomyelitis mice." (PMID 40241721, 2025). "Recently, Alves-Filho and his co-workers showed that Pkm2 contribute to autoimmune inflammation in experimental autoimmune encephalomyelitis (EAE) via fine-tuning Stat3 activation." (PMID 36633604, 2023). "In this report, we attempted to investigate the effect of a small molecular inhibitor of STAT3, i.e., Stattic, in a relapsing–remitting (RR) model of experimental autoimmune encephalomyelitis (EAE)." (PMID 34206429, 2021). "In addition, elevated STAT3 in brain myeloid cells was observed in MS patients and experimental autoimmune encephalomyelitis (EAE) model, proving its vital contribution to the regulation of myeloid cell function." (PMID 35356004, 2022). "Mice with targeted deletion of STAT3 in CD4+ T-cells do not develop experimental autoimmune uveitis (EAU) or experimental autoimmune encephalomyelitis (EAE), in part, because they cannot generate pathogenic Th17 cells." (PMID 22238646, 2012). "Deletion of the STAT3 binding site (STAT3-BS) in RORCE2 impaired RORγt expression and Th17 differentiation, resulting in reduced severity of experimental autoimmune encephalomyelitis (EAE)." (PMID 38172644, 2024). "We propose that IL-24–guided mitochondrial STAT3 constitutes a rheostat to blunt extensive STAT3 deflections in the nucleus, which might then contribute to a robust IL-10 response in Th17 cells and a restriction of immunopathology in experimental autoimmune encephalomyelitis." (PMID 35819408, 2022). "Experimental autoimmune encephalomyelitis (EAE) requires Stat3 activation, and the STAT3−/− CD4 mice were found to be resistant to EAE." (PMID 29056905, 2017). "Previous studies showed MSCs inhibited experimental autoimmune encephalomyelitis- (EAE-) derived CD4+ T cell activation by suppressing STAT3 phosphorylation via CCL2, and CCL2−/− MSCs could not ameliorate disease and decrease Th17 cells in EAE mice." (PMID 25918734, 2015). "A published study on experimental autoimmune encephalomyelitis indicated that STAT1 and STAT3, but not STAT5, regulated IL-9 mediated IL-17 production in T cells." (PMID 29887863, 2018).
gastric adenocarcinoma (27 papers, 2010 to 2026). "In gastric adenocarcinoma, STAT3, p-STAT3, and HIF-1α are associated with vasculogenic mimicry and impact patient survival." (PMID 33850110, 2021). "This inhibitory effect of propofol, however, decreased following the knockdown of hsa-miR-328-3p, which showed that it can block the proliferation of gastric adenocarcinoma by reducing the intensity of the STAT3 signal." (PMID 39309860, 2024). "To further investigate the combined contribution of YAP/TEAD and gp130/STAT3 pathway activation in a clinical context, we evaluated publicly available, The Cancer Genome Atlas stomach adenocarcinoma datasets (TCGA-STAD) to establish expression patterns." (PMID 37957015, 2024). "Research has also found that lycopene inhibits the proliferation of Helicobacter pylori-infected gastric adenocarcinoma cells by reducing ROS levels and inhibiting Jak1/Stat3 activation, Wnt/β-catenin signaling, and oncogene expression." (PMID 38287248, 2024). "Our data demonstrate the parallel deregulation of the Hippo and gp130/Stat3 pathways in the Gp130FF-dependent model of gastric adenocarcinoma." (PMID 37957015, 2024). "Z M Bai and colleagues reported a prominent decrease in hsa-miR-328-3p levels in gastric adenocarcinoma tissues, along with an increase in the levels of STAT3 and its downstream effectors, including MMP2, CCND1, and COX2." (PMID 39309860, 2024). "Janson reported that in gastric adenocarcinoma mouse models, STAT3 signaling increased the expression of miR-21, which revealed a link between the STAT3 and miR-21 levels." (PMID 39309860, 2024). "These authors showed that 5-fluorouracil in combination with BBR increases gastric adenocarcinoma cell death by suppressing survivin and STAT3 expression." (PMID 34885950, 2021). "IHC staining results confirmed that the STAT3/MSK1/NFATc2 axis was highly activated in mouse gastric adenocarcinoma samples." (PMID 32041943, 2020). "The immunhohistochemical study using phosphorylated STAT3 (pSTAT3) was positive in 3 out of 6 patients (including 2 patients with pancreatic and 1 with gastric adenocarcinoma)." (PMID 31139333, 2019). "Further, CD24 mediates gastric adenocarcinoma cell survival and invasion by activating STAT3 signaling and regulating extracellular matrix protein and VDR expression." (PMID 29772698, 2018). "Reduced levels of Cav-1 in human gastric adenocarcinoma cells resulted in significant STAT3 activation and enhanced cell proliferation." (PMID 29221162, 2017). "We investigated the inhibitory effect of pantoprazole on signal transducer and activator of transcription 3 (STAT3) activity and invasiveness of gastric adenocarcinoma cells, and the role of SH2-containing protein tyrosine phosphatase 1 (SHP-1) in mediating role." (PMID 30202514, 2018). "Wu's team discovered that a microRNA, miR-18a, a member of the miR-17–92 cluster, can positively regulate the activity of STAT3 by partially negatively regulating the STAT3 inhibitory gene PIAS3, thereby promoting the progression and spread of gastric adenocarcinoma." (PMID 39309860, 2024). "The previous reports showed that Ki-67, c-Met, vascular endothelial growth factor (VEGF), STAT3, hepatocyte growth factor and its receptor were highly expressed in AFP producing gastric adenocarcinoma tissues and cell lines as compared with AFP-negative gastric adenocarcinoma." (PMID 27057629, 2016).
primary immunodeficiency (27 papers, 2013 to 2025). "Dominant negative mutations in the transcription-factor STAT3 underlie the rare primary immunodeficiency Job's syndrome." (PMID 33014947, 2020). "Autosomal dominant hyper IgE syndrome (AD-HIES) is a primary immunodeficiency caused by a loss-of-function mutation in the Signal Transducer and Activator of Transcription 3 (STAT3)." (PMID 28587312, 2017). "Screening of primary immunodeficiency related genes showed a de novo heterozygous mutation in STAT3 (c.1412C>G p.(Pro471Arg), NM_139276.2) with potential pathological consequences." (PMID 26343524, 2015). "Besides, one of the deceased patients, clinically diagnosed with a primary immunodeficiency (FJD_0728); carried a variant on the STAT3 gene (p.Asn175His), in addition to one pathogenic variant in the recessive SRD5A3 gene." (PMID 35725860, 2022). "The critical role of STAT3 in lymphocyte biology was highlighted by the discovery that loss-of-function (LOF) mutations in STAT3 cause the primary immunodeficiency autosomal dominant hyper IgE syndrome (AD-HIES), which is characterized by defects in both T and B cells." (PMID 29472924, 2018). "To date, only 12 patients with DCM have been described who carried mutations associated with primary immunodeficiencies, all within the IL-12/IFN-γ and STAT3 axes." (PMID 36166305, 2022). "One vaccine challenge study was performed for each of the following strains of mice with a primary immunodeficiency: Stat4 KO, Ifngr KO, mut-Stat3, Dectin-1 KO, Rag-1 KO." (PMID 35071044, 2021). "On the one hand, severe fungal infections are associated with monogenic primary immunodeficiencies such as defects in STAT1, STAT3 or CARD9, recently discovered as novel clinical entities." (PMID 23629947, 2013). "It is not classified as a primary immunodeficiency per se, but may arise in the context of acquired somatic mutations (e.g., STAT3, DDX3X, or BCOR) or immune dysregulation affecting EBV control." (PMID 40863427, 2025). "People with rare primary immunodeficiencies (PID) in a variety of signaling pathways, including the IL-12/IFNγ axis and STAT3 pathway, have also been identified with disseminated coccidioidomycosis (DCM) and the mutations are thought to make them more susceptible." (PMID 35071044, 2021). "However, over the years, eight case reports of allogeneic hematopoietic stem cell transplant (HSCT) for STAT3-HIES have been published, three of them performed following the diagnosis of non-Hodgkin’s B cell lymphoma, which is a known complication of this primary immunodeficiency." (PMID 33523338, 2021).